FLT3 (fms related receptor tyrosine kinase 3)
Diseases named in the same sentence as FLT3 in open-access papers (continued):
Sharing a sentence is not in itself a finding about the gene and the disease.
COVID-19 (8 papers, 2021 to 2024). A disease caused by infection with severe acute respiratory syndrome coronavirus 2. "Treatment with dupilumab for acute COVID-19 was also associated with a larger decline in eotaxin, IL-12p40, IP-10, and FLT3, and with an increase in the anti-inflammatory cytokine IL-1Ra." (PMID 38312212, 2024). "The approval of baricitinib as an effective treatment for severe COVID-19 concurs with our finding because this intervention disrupts FLT3 function by inhibiting JAK signaling." (PMID 39650666, 2024). "At <6 DPOS, a model with FLT3, IL-17, IL-6, IL-15 emerged as the minimal cytokine set that explained 62% of variability in COVID-19 hospitalization (Akaike information criterion or AIC = 41.4; n = 49)." (PMID 39650666, 2024). "Therefore, they suggested that stimulation of autophagy and HIF-1α by COVID-19 may be a marker for AML patients, especially those with FLT3-ITD mutations." (PMID 38360719, 2024). "Therefore, COVID-19-stimulated autophagy and HIF-1 could serve as markers of AML patients, especially patients with FLT3-ITD mutations." (PMID 37189112, 2023). "Therapeutic strategies for COVID-19 patients are complex, and so the synergistic effects of BTK, FLT3, and EGFR in ALI should also be highlighted in the development of broad-spectrum antiviral compounds that boost the innate response." (PMID 36362264, 2022). "Further, the FLT3 inhibitor gilteritinib and EGFR inhibitor abivertinib have also shown great promising potential in treating COVID-19." (PMID 36362264, 2022). "Several enzymes can be used as a target for COVID-19 therapeutics including PI3K ̧ mTOR, growth factor receptor, RAF, MAP2K2, FLT3, AXL, AKT, and matrix metalloprotease MMP2 and MMP9." (PMID 35251015, 2022). "In our study, the levels of seven cytokines in COVID-19 patients (IL-6, IP-10, IL-8, MIG, MIP-1β, IL-18, TNF-α) were different from those in healthy controls, while M-CSF, MCP-1, FLT-3, VEGF, IL-1RA, EGF, eotaxin and MCP-1 were not different." (PMID 34539644, 2021).
Hypertension (8 papers, 2015 to 2025). The presence of chronic increased pressure in the systemic arterial system. "As for multi-target inhibitors, Ilorasertib (ABT-348) targeting Aurora kinase A/B, VEGFR/PDGFR and Src family, and ENMD-2076 targeting Aurora kinase A, VEGFR2/FGFR/Flt-3/c-Kit, were found to cause more DLTs, such as pancreatic disease and hypertension, fatigue, cholecystitis, and QTc prolonged." (PMID 30642372, 2019). "Ibrutinib-specific off-targets LCK, JAK3, and FLT3 were predicted to trigger inflammation processes related to hypertension; ERBB2, BLK, SRC, and CSK were predicted to trigger oxidative stress and endothelial dysfunction; and CSK were predicted to trigger the RAAS overactivation." (PMID 40744952, 2025). "Furthermore, both drugs suffer from a poor kinase selectivity profile, leading to hand-foot syndrome related to multitargeted tyrosine kinase inhibition, overlapping hematopoietic toxicities due to dual inhibition of FLT3 and KIT and high-grade hypertension linked to VEGFR2 inhibition." (PMID 40018846, 2025). "Previous clinical studies have shown that cabozantinib toxicity, which mainly manifests as diarrhoea, nausea, fatigue, decreased appetite, hand–foot syndrome and hypertension is due to the direct inhibition of VEGFR, FLT3 and KIT kinases, primary cabozantinib targets." (PMID 40437874, 2025). "Statistically significant increases were seen in vascular AEs overall with use of FLT3 inhibitors (RR = 1.52, 95% CI 1.05 to 2.19, p = 0.02, I2 = 0%) though individual vascular AEs (e.g. cardiac event, hypertension, etc.)were no different between FLT3 inhibitor and control groups." (PMID 33287892, 2020).
acute monocytic leukemia (7 papers, 2012 to 2022). Acute monoblastic leukemia (AML-M5), is one of the most common subtypes of acute myeloid leukemia (AML) that is either comprised of more than 80% of monoblasts (AML-M5a) or 30-80% monoblasts with (pro)monocytic differentiation (AML-M5b). "A 22-year-old male was diagnosed with acute monocytic leukemia with FLT3-ITD and DNMT3A mutations and pulmonary infection." (PMID 29843647, 2018). "In situ PLA readily detected association of endogenous DEP-1 and FLT3 in the human acute monocytic leukemia cell line THP-1, which was enhanced by FLT3 ligand (FL) stimulation in a time-dependent manner." (PMID 23650535, 2013). "Therefore, in this article, we present a rare case of HLH that occurred at the stage of induction chemotherapy in a patient with acute monocytic leukemia with FLT3-ITD and DNMT3A mutations." (PMID 29843647, 2018). "Therefore, he was clinically diagnosed with acute monocytic leukemia with FLT3-ITD and DNMT3A mutations and pulmonary infection." (PMID 29843647, 2018). "The acute monocytic leukemia-derived THP-1 cells express wild-type Flt3." (PMID 34835169, 2021).
colon carcinoma (7 papers, 2017 to 2025). "The missense mutation in FLT3 has been earlier detected in a colon carcinoma and an endometrioid carcinoma (COSM946463)." (PMID 29287594, 2017). "However, when patient-derived tumor cells from colon cancer with FLT3 amplification were used for further study, tumor growths could not be inhibited by either regorafenib or sorafenib." (PMID 34194582, 2021). "Our data from the HCC cell lines and xenograft tumors further verified the mechanism of action of DBPR114 reported previously in AML and colon cancer cell lines, in which DBPR114 modulated FLT3 and AURKA/B inside the cells and induced the accumulation of multinucleated cells." (PMID 35062934, 2022).
liver cancer (7 papers, 2019 to 2025). An epithelial or non-epithelial malignant neoplasm that arises from the liver. "In samples with high expression in the control group of FLT3, it is predominantly enriched in Kaposi liver cancer Met and Gaussmann MLL-AF4 fusion targets B." (PMID 40362543, 2025).
mastocytosis (7 papers, 2014 to 2024). A clonal myeloproliferative neoplasm characterized by the proliferation and accumulation of neoplastic mast cells in one or multiple organs or organ systems. "It was approved in 2017 by the US FDA for the management of AML patients with FLT3 mutations and has also recently been accepted for those newly diagnosed with the FLT3 mutation and or systemic mastocytosis." (PMID 36293564, 2022). "Midostaurin is approved for systemic mastocytosis and remains the sole agent approved in combination with induction and consolidation chemotherapy for newly diagnosed FLT3-mutated AML patients." (PMID 34829820, 2021). "FLT3 is one of the most frequently mutated genes in AML, while KIT oncogenic mutations occur in 80–90% of mastocytosis." (PMID 32708273, 2020). "This review highlights the central roles of SFKs in AML and mastocytosis, and their interconnection with FLT3 and KIT oncoproteins." (PMID 32708273, 2020). "It has to be noted, that IC50s in the mutant-KIT D816 mastocytosis cell lines in response to crenolanib are ∼100-fold less sensitive compared to (FLT3 ITD+) MOLM14 cells." (PMID 29137311, 2017).
monocytic leukemia (7 papers, 2015 to 2025). "Integrin αVβ3 has been reported to be more expressed in AML cells especially CD34‐positive cells, monocytic leukemias, patient with NPM, and FLT3‐ITD." (PMID 35155195, 2021).
neuroblastoma (7 papers, 2012 to 2023). Neuroblastoma (NB) is the most common solid, extracranial childhood tumor. "By analogy with neuroblastoma, we can assume that an additional transcription factor is required to maintain N-MYC oncogene expression in AML patients carrying the FLT3-ITD mutation." (PMID 37606386, 2023). "Next-generation sequencing analysis revealed FMS-like tyrosine kinase-3 (FLT3)-internal tandem duplication (ITD) and neuroblastoma RAS (NRAS) mutations." (PMID 34001105, 2021). "FL shows a significant proliferating and anti-apoptotic activity in neuroblastoma and neuroepithelioma lines suggesting that Flt-3 and its ligand are expressed in neural crest-derived tumors and promote survival and proliferation of their cell lines." (PMID 21876694, 2012). "The main objective of this work was to quantify the expression of some genes (C-MYC, N-MYC, SPT16, AURKA, AURKB) that are more characteristic biomarkers for neuroblastoma with poor prognosis, but less studied in AML patients, including carriers of FLT3-ITD mutation with high allelic load." (PMID 37606386, 2023). "Then, we decided to additionally determine the expression of the N-MYC oncogene and the nearest circle of regulatory genes (SPT16, AURKA, AURKB) whose expression is often elevated in neuroblastoma and remains unstudied in adult patients with AML, including FLT3-ITD mutation carriers." (PMID 37606386, 2023). "Similarly, a previous study found increased Flt3 expression following I/R-injury in a human neuroblastoma cell line, whilst silencing of Flt3 prevented I/R-injury in these cells, suggesting a mediating role for Flt3 during I/R-injury." (PMID 36479354, 2022). "Flt-3 is a transmembrane glycoprotein receptor structurally related to macrophage colony stimulating factor receptor-1 (CSF-1) and c-Kit, and it is expressed on several cell types including neuroblastoma cells." (PMID 21876694, 2012).
Splenomegaly (7 papers, 2014 to 2022). Abnormal increased size of the spleen. "Both expression levels of miR-126-5p and miR-13 were not correlated with sex, age, WBC, PLT, proportion of bone marrow primordial cells, hepatomegaly, splenomegaly, lymph node enlargement, and FLT3-ITD (P > 0.05)." (PMID 35401744, 2022).
brain tumors (6 papers, 2007 to 2022). "TG02 is an inhibitor of CDKs, JAK2 and FLT3 able to penetrate the blood-brain barrier and is therefore an interesting therapeutic for brain tumors." (PMID 33918704, 2021).
kidney cancer (6 papers, 2015 to 2021). Primary or metastatic malignant neoplasm involving the kidney. "For example sorafenib, an FDA-approved drug for thyroid, liver and kidney cancers, potently binds to FLT3 and FLT3-ITD with Kd values of 13 nM and 95 nM respectively and has shown activity against AML in the clinic." (PMID 30686755, 2019).
lymphoid leukemia (6 papers, 2012 to 2025). A malignant lymphocytic neoplasm of B-cell or T-cell lineage involving primarily the bone marrow and the peripheral blood. "The fms-like tyrosine kinase 3 (Flt3) is a cell surface receptor that is expressed by various hematopoietic progenitor cells (HPC) and Flt3-activating mutations are commonly present in acute myeloid and lymphoid leukemias." (PMID 28498310, 2017). "A variety of other cell lines express mutated FLT3, including lymphoid leukemia cell lines." (PMID 41287669, 2025). "Future work will expand the panel of CML cell lines, FLT-3-ITD mutated AML and other common subtypes and incorporate lymphoid leukemia models to enable a more comprehensive comparison across hematologic lineages to assess the generalizability potential of the observed signaling dynamics." (PMID 40986633, 2025). "In addition, a retroviral insertional mutagenesis screen in the FLT3/ITD knock-in background identified a high proportion of lymphoid leukemias." (PMID 22643831, 2012).
sarcoma (6 papers, 2013 to 2024). A usually aggressive malignant neoplasm of the soft tissue or bone. "New studies have explored the use of gilteritinib for extramedullary recurrence of APL with FLT3 mutations, showing rapid and sustained regression of the sarcoma." (PMID 39911670, 2024). "To address whether expression of mutant, constitutively active FLT3 would affect radiation response, we utilized a set of GFP-based reporter assays in sarcoma U2OS cells that allow measurements of distinct DSB repair pathways." (PMID 24367670, 2013). "Based on this, there is very little evidence to speculate about the association between FLT3 ITD mutations and occurrence of GS even why we were not able to demonstrate the presence of FLT3-ITD mutation in the mastoid sarcoma tissue." (PMID 24109526, 2013).
Sepsis (6 papers, 2011 to 2025). Sepsis is defined as life-threatening organ dysfunction caused by a dysregulated host response to infection. "Further investigation is warranted to explore the synergistic potential of Flt3 therapy with other established therapeutics, such as IL-7, in the management of sepsis." (PMID 39720718, 2024). "However, they reported that CD135 (Flt3)+ MPPs are mainly responsible for the sepsis-induced hematopoietic regenerative response, which includes MPP amplification and their rapid differentiation into granulocytes and monocytes." (PMID 39859383, 2025). "Thus, Flt3 is hypothesized to reduce T cell apoptosis in sepsis." (PMID 39720718, 2024).
thyroid cancer (6 papers, 2016 to 2025). "Interestingly, phosphorylation of other RTKs such as EGFR, ERBB2, and FLT-3 have recently been shown to be promoted when EcSOD is overexpressed in thyroid cancer cells." (PMID 29296173, 2017).
ovarian carcinoma (5 papers, 2020 to 2025). A malignant neoplasm originating from the surface ovarian epithelium. "FLT3 is highly expressed in oocytes and related to follicular growth and maturation; moreover, it has been reported to be highly expressed in ovarian cancer tissues, promoting ovarian cancer metastasis and angiogenesis." (PMID 32825655, 2020). "Defactinib has recently been granted breakthrough therapy designation by the FDA for the treatment of ovarian cancer, which thus could facilitate a timely investigation of the benefits of PTK2B/FAK inhibition also in FLT3-ITD mutated AML patients, based on the results of this study." (PMID 36056084, 2022).
acute megakaryoblastic leukemia (4 papers, 2013 to 2024). Acute megakaryoblastic leukemia (AMKL) is a form of acute myeloid leukemia (AML) that occurs predominantly in childhood and particularly in children with Down syndrome (DS-AMKL). "In particular, miR-125 overexpression was identified in different AML subtypes characterized by specific chromosomal abnormalities, including AML1/ETO, PML/RARα and FLT3 translocations, and in Down Syndrome-associated acute megakaryoblastic leukemia (AMKL)." (PMID 24145746, 2013). "Primary blast samples from patients harboring a MLL rearrangement (MLLr), FLT3-internal tandem duplication positive (FLT3-ITD+), or with acute megakaryoblastic leukemia (AMKL) were plated on mesenchymal stromal cells and treated with DMSO or increasing concentrations of indicated compounds." (PMID 31097698, 2019).
Arthritis (4 papers, 2012 to 2020). Inflammation of a joint. "Blockade of Flt3 signaling using a synthetic Flt3 inhibitor alleviates signs of synovitis and cartilage destruction in antigen-induced model of arthritis." (PMID 23082191, 2012). "In line with our study using crotonoside, other Flt3 inhibitors, such as sunitinib and sorafenib, approved by Food and Drug Administration (FDA) for chemotherapy, were also demonstrated to be capable of reducing arthritis induced by methylated BSA or type II collagen in murine models." (PMID 33182776, 2020).
autoimmune disease (4 papers, 2015 to 2025). A disorder resulting from loss of function or tissue destruction of an organ or multiple organs, arising from humoral or cellular immune responses of the individual to their own tissue constituents. "As epitope spreading or antigen spreading is observed in autoimmune diseases or cancer research and FLT3 is only one of numerous antigens expressed on tumor cells, we also thought to test whether VRP vaccines could elicit antibody responses against antigens other than FLT3." (PMID 35686131, 2022). "The most prominent genetic risk factors are alleles within the HLA class, particularly HLA-DRB1, while a large number of non-HLA genes (FLT3, IRF5, STA4) involved in autoimmune diseases are interlinked in a network that regulates IFN signalling and dendritic cell and T cell function." (PMID 40495344, 2025).
bladder cancer (4 papers, 2017 to 2025). "This study highlights the critical role of FLT3/FLT3LG in BCG immunotherapy for bladder cancer and provides novel candidate targets for optimizing BCG immunotherapy in future studies." (PMID 38213738, 2024).
cervical cancer (4 papers, 2022 to 2025). A primary or metastatic malignant neoplasm involving the cervix. "Recently published data from patients with breast (FLT3) and cervical cancer (FLT3LG) stay in line with our results." (PMID 38327131, 2024). "To add adequate controls, we also knockout miR-155 in two other cell lines, the NB4 cells (a FLT3 WT AML cell line) and HeLa cell line (Cervical Cancer-Solid tumor) and conduct MTT assay to test the sensitivity to ADM." (PMID 36605494, 2023).
hypothyroidism (4 papers, 2021 to 2025). Abnormally low levels of thyroid hormone. "For example, the missense variant rs78534766 in ADCY7 and the FLT3 variant rs76428106 associated with large effects on hypothyroidism (OR = 1.4 and 1.37, respectively) but had a comparably small effect on TSH levels (s.d. = 0.04 and 0.08, respectively)." (PMID 41238958, 2025).
lupus (4 papers, 2016 to 2024). "In agreement with our animal studies, the percentage of FLT3+ B1 cells in Systemic Lupus Erythematosus (SLE) patients is significantly higher than healthy control." (PMID 27590507, 2016). "The higher proportion of Flt3+ B1 cells in systemic lupus erythematosus (SLE) patients suggests a potential role of the MYSM1/miR-150/Flt3 pathway in the pathogenesis of SLE." (PMID 39684760, 2024).
meningioma (4 papers, 2021 to 2026). A generally slow growing tumor attached to the dura mater. "FLT3 as a genetically supported candidate factor associated with meningioma risk." (PMID 41728071, 2026). "The macrophages in meningioma had one drug-target kinase that was significantly increased in expression compared to VS (FLT3), whereas VS had two drug-target kinases, FGFR2 and FGFR3." (PMID 41437121, 2025). "The expression of FLT3 in meningioma has been reported, however, the clinical significance in meningioma remains unclear." (PMID 34885009, 2021).
pancreatic cancer (4 papers, 2015 to 2022). "In a recent analysis of 2,400 pancreatic cancer patients of whom 82% were found to have mutated KRAS, mutations in BRAF, EGFR, HER2, FLT3, HRAS, PDGFRA, and PTEN were identified exclusively in KRAS wild-type patients, and even there, only rarely (8%)." (PMID 26161408, 2015). "FLT3 may be a potential biomarker for individualized pancreatic cancer prognosis." (PMID 35205822, 2022).
rheumatoid arthritis (4 papers, 2012 to 2020). A chronic, systemic autoimmune disorder characterized by inflammation in the synovial membranes and articular surfaces. "In knockout FL or FLT3 rheumatoid arthritis mouse models, increased OC formation and bone damage have been observed." (PMID 33182501, 2020).
stomach cancer (4 papers, 2021 to 2025). "To shed light on myeloid populations present in gastric tumors, we re-clustered the 10,546 myeloid cells in our dataset and identified fifteen subclusters which were subsequently determined to be either macrophages (CD68, CD14), dendritic cells (FLT3, FCER1A), or neutrophils (CSF3R)." (PMID 36550535, 2022).
acute GVHD (3 papers, 2018 to 2026). "The following factors were analyzed: hematological status at transplant, donor source, type of conditioning, the occurrence of acute GVHD, and the presence of FLT3/ITD mutation at transplantation and at day + 30 after procedure." (PMID 32333156, 2020).